BRCA2 (BRCA2 DNA repair associated)
Diseases named in the same sentence as BRCA2 in open-access papers (continued):
Sharing a sentence is not in itself a finding about the gene and the disease.
breast cancer (continued). "The modifying effect on the breast cancer risks of BRCA1 and BRCA2 carriers may explain some of the differences between the risk estimates from population based studies and high risk families." (PMID 11857015, 2002). "We conclude that bilaterality of breast cancer on its own is not strongly associated with BRCA1 and BRCA2 mutations when adjusted for age and family history." (PMID 11556836, 2001). "In sporadic breast cancer, LOH of BRCA1 of BRCA2 does not add decisive prognostic value as stated for familial breast cancer." (PMID 8630282, 1996). "The lower breast cancer-specific survival rate for BRCA2 compared with BRCA1, which is considered to have a poorer prognosis, may provide a glimpse into the proper long-term prognosis of BRCA2 but needs further investigation." (PMID 41083355, 2025). "This cohort study analyzed data from a large cohort of women with a diagnosis of breast cancer regardless of age, and we identified pathogenic or likely pathogenic variants in BRCA1 and BRCA2 in 4.4% of Asian patients, 8.1% of African American or Black patients, and 4.8% of White patients." (PMID 40952741, 2025). "Similarly, of the 913 patients who underwent GT in Post, 623 breast cancer patients were included, excluding ovarian cancer patients and those who underwent RRSO at or below the recommended age (35 years for BRCA1 and 40 years for BRCA2)." (PMID 40399479, 2025). "This appears to be a new finding compared to an earlier study of GATA3 mutations in familial breast cancer, where GATA3 mutations were found in 22% (7/32) of patients without BRCA1/1 mutations and not identified in patients with germline BRCA1 or BRCA2 mutations (n = 0/23)." (PMID 40439821, 2025). "Consequently, the inference reported with high confidence that metformin does not target BRCA2 in breast cancer." (PMID 40293950, 2025). "SERPINA3 is expressed at higher level in epithelial cells of BRCA1 and BRCA2 mutation carriers compared with non-carrier; this has previously been shown to confer invasiveness and epithelial-to-mesenchymal transition (EMT) phenotype to breast cancer cells." (PMID 38059556, 2024). "Currently, there are no ongoing applications of BRCA‐1 or BRCA‐2 gene replacement in breast cancer." (PMID 38827026, 2024). "BRCA PVs are known to be correlated with younger age at diagnosis of breast cancer- median 38 years in BRCA1 mutation and 41 years in BRCA2 mutation, as compared to 43 years in non-BRCA mutated women, and for BRCA1- a higher incidence of high-grade tumors (87%) and triple-negative disease (73%)." (PMID 38365640, 2024). "For example, our study lacked information on genetic history or predisposition for breast cancer (e.g., BRCA1/BRCA2), though this would likely not be related to air pollution exposure, and therefore may not be a true confounder." (PMID 38630334, 2024). "Our study echoes this trend, as evidenced by our findings on DFS and OS rates among groups categorized by PVs in associated genes (i.e., BRCA1, BRCA2, and HR-DDR or inherited breast cancer cases) and those with PVs in non-associated genes (i.e., other breast cancer cases)." (PMID 38893140, 2024). "The increased breast cancer risk after long-term use, especially before the first child that was observed in the retrospective results were not supported by the prospective analyses, neither for BRCA1-pV carriers nor for those with pV in the BRCA2 gene." (PMID 39259360, 2024).
breast cancer (continued). "To determine if BRCA1/2 may facilitate HR-dependent lesion bypass of APOBEC-induced DNA damage in breast cancer, we assessed SBS13 mutations for replicative asymmetry associated with deamination of the lagging strand template in the absence of BRCA1 or BRCA2." (PMID 37532520, 2023). "However, we noted that BRCA1 mutated cases displayed a higher incidence of triple‐negative (TN) breast cancer than in BRCA2 cases, regardless of ALDH2 genotypes." (PMID 36345163, 2023). "To test this hypothesis, we used breast cancer samples and the BRCA1 and BRCA2 genes as a model." (PMID 37046838, 2023). "Furthermore, in vivo study in 4T1 induced breast cancer mouse model showed that the tumor growth rate and final volume were decreased significantly in the mouse group treated intravenously with BRCA1 + NPs and BRCA2 + NPs formulations." (PMID 36631481, 2023). "Another possible explanation for not finding a risk-reducing effect of RRSO on breast cancer risk is that the optimal timing of RRSO to prevent tubal/ovarian cancer is between 35 and 40 years for BRCA1 GPV carriers and between 40 and 45 years for BRCA2 GPV." (PMID 37046756, 2023). "Similarly, germline breast cancer susceptibility gene variants, such as BRCA1 and BRCA2, are not considered to contribute towards the traditional definition of a cancerized field." (PMID 35362092, 2022). "Examples of extensive genomic databases like deCODE genetics Iceland show that holding this data has numerous ethical implications, e.g., how to deal with the stored information on carriership of the breast cancer genes BRCA-1 and BRCA-2 and whether to inform and screen affected individuals." (PMID 35323196, 2022). "We found that breast cancer patients lacking BRCA2-001/Short expression in any tumor (primary or recurrences) had significantly improved overall survival (median 87 vs. 121 months), suggesting it could be a prognostic biomarker." (PMID 36344544, 2022). "Through Next Generation sequencing (NGS), we analyzed all of the coding regions and the exon–intron junctions of BRCA1 and BRCA2 genes—the two most important genes in hereditary breast cancer—in fifty-one women from Burkina Faso with early onset of breast cancer with or without a family history." (PMID 34717758, 2021). "However, the risk of developing breast cancer by HRT may differ between BRCA1 and BRCA2 pathogenic variant carriers, and therefore we need to continue discussing carefully whether long-term estrogen treatment does not really increase the risk of breast cancer incidence." (PMID 34071148, 2021). "In addition, a reverse association of the prognostic value of hormone receptor status was observed between breast cancer patients with or without germline BRCA pathogenic variants, particularly in the case of BRCA2 pathogenic variants." (PMID 33579978, 2021). "The risk of breast cancer does not appear to be different between BRCA1 and BRCA2 carriers." (PMID 34356066, 2021). "A total of 51 African women from Burkina Faso affected by breast cancer have been selected by genetic counseling at the CERBA/LABIOGENE laboratory of the University of Ouagadougou (Burkina Faso) to perform a genetic testing for the screening of BRCA1 and BRCA2 genes." (PMID 34717758, 2021). "Survival was not significantly different between BRCA1, BRCA2 and non-BRCA carriers on enhanced screening with 20-year breast cancer specific survival particularly good in 60 BRCA1 carriers at 91.5% (78.5–96.8) compared to 59 BRCA2 at 85.1% (64.1–94.3) and 275 non-BRCA 84.7% (76.5–90.3)." (PMID 34312777, 2021). "In contrast, there is no specific breast cancer subtype in BRCA2 carriers." (PMID 33804295, 2021).
breast cancer (continued). "It is also suggested to apply chemoprevention to prevent breast cancer in female with BRCA mutation carriers without prior breast cancer, but this is, if necessary, only suggested for female with BRCA2 mutation, and it is questionable if it should be advised to these women." (PMID 33996049, 2021). "Indeed, although platinum-based therapies are not the standard of care for breast cancer, they can have utility in carriers of pathogenic mutations in BRCA1 and BRCA2 genes, who are particularly sensitive to platinum-based drugs." (PMID 34072979, 2021). "Identification of disease-associated genetic changes in breast cancer susceptibility genes, including BRCA1, BRCA2 and PALB2, not only has actionable implications for carriers, but also for the additional members of their family who are found to carry the high-risk variant." (PMID 33113089, 2021). "First, 22 women in the TCGA ovarian cancer category had BRCA1 or BRCA2 germline mutations, while another 27 in the control group had BRCA1 or BRCA2 mutations (these were breast cancer patients, included here as controls because they were non-ovarian cancer women patients)." (PMID 33750420, 2021). "The BCRAT tool is an implementation of the Gail model, which is a statistical model that estimates 5-year breast cancer risk in women without a personal history of breast cancer and without known mutations in high-risk breast cancer genes such as BRCA1 and BRCA2." (PMID 34521662, 2021). "In detail, 8 BRCA2Cis DH carriers, 3 BRCA2 SH carriers, 4 relatives, 8 non-carriers, 24 breast cancer patients with unknown BRCA status and 13 healthy Tunisian women were investigated using the four selected STR markers." (PMID 34456966, 2021). "In terms of the first DFS event, second primary malignancies (breast cancer: 17.0% vs. 12.2%, P = 0.009; non-breast cancer: 4.3% vs. 1.9%, P = 0.02) were more frequent in the BRCA1 cohort while distant recurrences were less frequent (10.4% vs. 15.4%, P = 0.02) as compared to the BRCA2 cohort." (PMID 33579978, 2021). "The latest reports show though that deleterious BARD1 variants may be the reason for hereditary breast cancer in BRCA1 and BRCA2 negative families." (PMID 33114377, 2020). "The natural history of breast cancer among BRCA2 carriers has not been clearly established." (PMID 32939053, 2020). "Among 2272 BRCA1 and 1605 BRCA2 mutation carriers without a previous diagnosis of cancer or RRM, 269 BRCA1 and 157 BRCA2 mutation carriers were diagnosed with breast cancer during follow-up (mean follow-up time 5.4 and 4.9 years for BRCA1 and BRCA2, respectively)." (PMID 31948486, 2020). "In the present study, we determined the contribution of pathogenic RECQL variants to hereditary breast cancer in 302 early-onset and familial BRCA1 and BRCA2 negative patients with ER positive and/or PR positive breast cancer in a South Asian population from Pakistan." (PMID 33342430, 2020). "Furthermore, although the splicing vector pSAD was initially developed to study the breast cancer genes BRCA1 and BRCA2, it has also been demonstrated to be a powerful tool to test other disease genes such as SERPINA1, CHD7, and UGT1A1, as well as others currently under investigation." (PMID 32211025, 2020). "BRCA1 and BRCA2 germline pathogenic variants were found in 7.3% of the IBC patients, 6.3% had a mutation in other cancer genes (PALB2, CHEK2, ATM and BARD1), and 1.6% had a germline pathogenic variant in other genes not related with breast cancer." (PMID 32075053, 2020).
breast cancer (continued). "None of the 211 BRCA2 breast cancers were identified by mammography only." (PMID 32333294, 2020). "Moreover, common HMMR variants modify the risk of developing breast cancer for carriers of BRCA1, but not BRCA2, mutations." (PMID 32231069, 2020). "Moreover, one-third of all breast cancer occurs within the families are not related to either BRCA1 or BRCA2, indicating that other low penetrate genes are involved in the development of familial breast cancer." (PMID 33013205, 2020). "Moreover, in HPV-positive breast cancer patients BRCA1 and BRCA2 were decreased (both P < 0.001) compared to the HPV-negative group., suggesting that the role of HPV in breast cancers could be accomplished through interacting with these proteins." (PMID 30642295, 2019). "A recent study suggests approximately a third of newly diagnosed breast cancer patients in the US are not offered BRCA1/BRCA2 genetic tests, despite the fact that the result may inform their treatment." (PMID 30689103, 2019). "By contrast, there is no characteristic breast cancer subtype in BRCA2 carriers." (PMID 30828495, 2019). "Similarly, BRCA1-, but not BRCA2-, breast cancers was also associated with higher PD-1 (PDCD1) expression compared to BRCA-proficient breast cancers in both WSI and TCGA cohorts (PBRCA1: 0.013 and 7.2 x 10−3, respectively." (PMID 31022191, 2019). "After excluding the BRCA2 p.Glu1308Ter carrier (blind control), which was properly identified, four probands in 48 (8.3%) were found to carry a pathogenic variant in a non-BRCA breast cancer gene." (PMID 31780696, 2019). "None of the breast cancer risk factors examined differed between BRCA1 and BRCA2 carriers." (PMID 30175445, 2019). "Breast cancer (BC) prognosis in BRCA1 and BRCA2 mutation carriers has been reported contradictorily, and the significance of variables influencing prognosis in sporadic BC is not established in BC patients with hereditary BRCA1/BRCA2 mutations." (PMID 31141992, 2019). "A total of 325 Japanese women with breast cancer (BC) (with or without invasive cancer) were referred for genetic counseling and underwent genetic testing for mutations in the BRCA1 and BRCA2 genes in Showa University Hospital between December 2011 and August 2016." (PMID 30652428, 2019). "On the other side, RAD54B is a telomere-related gene involved in DNA repair process, and coding-missense changes of this gene have been found in familial breast cancer cases not explained by mutations in the best-known high susceptibility genes BRCA1 and BRCA2." (PMID 30211214, 2018). "The BRCA2 inactivation through EMSY amplification might be important in the tumorigenesis of a substantial proportion of non-inherited sporadic breast cancer." (PMID 29707112, 2018). "Previous study demonstrated that AURKA is commonly overexpressed in breast cancers with BRCA2 mutation and overexpressed AURKA could also suppress BRCA2 in ovarian cancer, indicating that there exists a negative correlation between AURKA and BRCA2." (PMID 28147341, 2017). "Personal history of breast cancer, with and without a family history of ovarian cancer, was the primary criteria used to select individuals for this study from among all those who had previously tested negative for BRCA1 and BRCA2 mutations." (PMID 28281021, 2017). "In addition, consanguinity should protect against breast cancer caused by BRCA1 and BRCA2 which is not a case in this population." (PMID 29157216, 2017).
breast cancer (continued). "Therefore, regardless of family history, all men with breast cancer should be routinely screened for BRCA1 and BRCA2 mutations." (PMID 27377827, 2016). "Interestingly, BRCA2 mRNA levels did not change in response to miR-19a or miR-19b in the breast cancer cell lines MDA-MB-231, MCF7, and BT-20." (PMID 27630665, 2016). "However, none of the SNPs showed associations with breast cancer risk, including rs11099601, which had a P-value of 0.89 and 0.78 in BRCA1 and BRCA2 carriers respectively." (PMID 27792995, 2016). "The aim of this study was to evaluate the prevalence of this variant and determine its contribution to the development of breast cancer in sporadic cases and also in members of breast cancer families who tested negative or positive for a deleterious mutation in BRCA1/BRCA2." (PMID 25674498, 2015). "If this experimental finding holds in pre-clinical or clinical studies, many more breast cancer patients could benefit from PARP inhibitor therapy, because HR repair is deficient in many cancers without BRCA1 or BRCA2 mutations." (PMID 25769025, 2015). "Unfortunately, in this study, we collected mammary tumor samples soaked in RNAlater solution; therefore, we could only test BRCA2 mRNA levels and could not determine BRCA2 protein levels by western blotting or immunohistochemistry." (PMID 26202431, 2015). "Genetic factors play an important role in breast cancer (BC) development, including the presence of BRCA1, BRCA2, ATM, and other genes, but only 5% of BC incidence can be explained by mutation in these high-penetrance genes." (PMID 25636233, 2015). "Tamoxifen appears to be effective in reducing breast cancer in carriers of BRCA2 but not in carriers of BRCA1.17,18 The differential effect of tamoxifen may be due to the differential expression of the estrogen receptor in tumors of BRCA carriers." (PMID 26886774, 2015). "The majority of these mutations identified in familial breast cancer result in the partial or complete deletion of exons or intronic sequence inserts, which may ultimately yield non-functional, truncated BRCA1 and BRCA2 proteins." (PMID 25624909, 2015). "35.0% (35/100) breast cancer tissues were positive for PARP1 expression in the nuclei; 34% (34/100) breast cancer tissues were positive for BRCA1 expression in both the nuclei and cytoplasm, 33% (33/100) breast cancer tissues were positive for BRCA2 expression in both the nuclei and cytoplasm." (PMID 25865228, 2015). "Primary breast cancer treatments may be different for BRCA1 and BRCA2 mutation carriers compared to non-carriers, mostly related to different pathological features of tumours in carriers (part A)." (PMID 25816289, 2015). "This study screened Australian individuals with breast cancer who had been referred to a Familial Cancer Centre for genetic testing and in whom no pathogenic BRCA1 and BRCA2 variant could be identified." (PMID 26283626, 2015). "In this study, we performed germline mutation analysis of the entire coding region of PALB2 in a cohort of 1996 breast cancer index cases referred to familial cancer clinics for genetic testing and tested negative for BRCA1 and BRCA2 mutations as well as 1998 Australian cancer-free female controls." (PMID 26283626, 2015).